HOXA-AS2 (HOXA cluster antisense RNA 2)
Synonyms: HOXA3as
Gene: Long non-coding RNA gene on chromosome 7 (27,107,777 to 27,134,302, forward strand). Ensembl gene ENSG00000253552.
Diseases named in the same sentence as HOXA-AS2 in open-access papers:
HOXA-AS2 is named in the same sentence as 43 diseases in open-access papers, as found by Europe PMC text mining. Sharing a sentence is not in itself a finding about the gene and the disease. The quoted sentences say what the papers report.
breast carcinoma (9 papers, 2015 to 2022). "HOXA-AS2 is upregulated in breast cancer and its silencing inhibits the progression of breast cancer." (PMID 30669611, 2019). "Functional studies indicated a role of HOXA-AS2 in cell proliferation, apoptosis, migration and invasion of breast cancer cells." (PMID 28545023, 2017). "Additionally, HOXA-AS2 is aberrantly expressed in malignant tumors such as gastric cancer, cholecystitis, hepatocellular carcinoma and breast cancer." (PMID 36135086, 2022). "HOXA-AS2 has been found to play a role in the development of gastric cancer, liver cancer, breast cancer, bladder cancer, intestinal cancer, and pancreatic cancer and has been reported to be related to tumor size and pathological stage and patient prognosis in gastric cancer." (PMID 32760226, 2020). "HOXA cluster antisense RNA 2 (HOXA-AS2), transcribed between the HOXA3 and HOXA4 genes, has been implicated in oncogenic promotion in pancreatic cancer, breast cancer, colorectal cancer, GC, bladder cancer, HCC, thyroid cancer, gallbladder carcinoma, lung cancer, osteosarcoma, glioma, and leukaemia." (PMID 33375038, 2020). "The data were in accordance with the HOXA-AS2 expression profile obtained by lncRNA PCR array in HA22T/VGH cells and indicated that sorafenib may mediate HOXA-AS2 down-modulation also in renal and breast cancer cells." (PMID 31235746, 2019). "The expression level of HOXA-AS2 was detected by qRT-PCR in 38 pairs of breast cancer tissues (Tumor) compared with corresponding adjacent normal tissues (Normal), and we found that HOXA-AS2 expression was significantly up-regulated in tumor tissues compared with normal tissues." (PMID 28545023, 2017). "c) Silencing of HOXA-AS2 significantly suppressed carcinogenesis of breast cancer." (PMID 28545023, 2017). "Thus, HOXA-AS2 can be a potential prognostic marker and therapeutic target for breast cancer." (PMID 30669611, 2019). "However, the role of HOXA-AS2 in breast cancer development, invasion and metastasis remains unknown." (PMID 28545023, 2017). "Although numerous observations have demonstrated HOXA-AS2 and SNHG8 play vital roles in the development of various cancer including non-small cell lung cancer and breast cancer, gastric cancer." (PMID 33520460, 2021). "The results obtained in the present study indicate that sorafenib mediated the up-regulation of GAS5 and the down-regulation of HOTTIP and HOXA-AS2 in most HCC, renal and breast cancer cells and probably their expression modulation may lead to a less aggressive cancer phenotype of the cells." (PMID 31235746, 2019). "Interestingly, HOXA-AS2 was significantly downregulated or represented no significance in breast cancer, colorectal cancer, liver cancer, lung cancer and esophagus cancer tissues." (PMID 26384350, 2015).
glioma (9 papers, 2020 to 2024). A benign or malignant brain and spinal cord tumor that arises from glial cells (astrocytes, oligodendrocytes, ependymal cells). "HOXA-AS2 is involved in the pathogenesis of glioma and regulates glioma cell viability, cell migration, and invasion, participating in the occurrence of vasculogenic mimicry and apoptosis." (PMID 35174152, 2022). "We found that HOXA-AS2 is overexpressed only in aggressive (IDHwt) glioma and GSC lines." (PMID 35563134, 2022). "HOXA cluster antisense RNA 2 (HOXA-AS2) also emerge as an actor of glioma biology." (PMID 35563134, 2022). "Thus, we aimed in this study to identify the expression pattern of lncRNA homeobox A cluster antisense RNA 2 (HOXA-AS2) in glioma and decipher its role in immune tolerance and glioma progression." (PMID 35181676, 2022). "HOXA-AS2 has been confirmed to promote the metastasis of glioma." (PMID 33430870, 2021). "In glioma, HOXA Cluster Antisense RNA 2 (HOXA-AS2) was upregulated and promoted biological behaviors of malignant glioma and vasculogenic mimicry (VM) formation via the miR-373/EGFR axis." (PMID 37239411, 2023). "Here, we investigated the role of the long non-coding RNA HOXA-AS2 in GSC biology using descriptive and functional analyses of glioma samples classified according to their isocitrate dehydrogenase (IDH) gene mutation status, and of GSC lines." (PMID 35563134, 2022). "We found aberrant upregulation of lncRNA HOXA-AS2, lysine demethylase 2A (KDM2A), and jagged 1 (JAG1) and a downregulation of microRNA-302a (miR-302a) in glioma specimens." (PMID 35181676, 2022). "To determine whether these transcription factors were direct HOXA-AS2 targets, we analyzed the correlation between their expression level and that of HOXA-AS2 in glioma using the RNA-seq data of the 134 IDHwt glioma samples from the “TCGA cohort”." (PMID 35563134, 2022). "Our data confirmed previous observations made in glioma samples classified according to the 2007 WHO criteria (i.e., GBM and lower-grade glioma) that HOXA-AS2 is upregulated in glioma and that its expression level is positively associated with advanced tumor stages." (PMID 35563134, 2022). "RT-qPCR analysis (n = 10 control samples, n = 8 IDHmut and n = 43 IDHwt glioma samples, and n = 6 GSC lines) confirmed that HOXA-AS2 was expressed only in IDHwt glioma samples and GSC lines, while it was virtually undetectable in control and IDHmut glioma samples." (PMID 35563134, 2022). "As dozens of HOXA-AS2 isoforms are predicted by the Gencode gene project, we first assessed the expression of all HOXA-AS2 isoforms in three normal brain tissue samples (control), eight IDHwt and five IDHmut glioma samples, and two GSC lines using a strand-oriented RNA-seq approach." (PMID 35563134, 2022). "We could confirm that HOXA-AS2 was expressed in IDHwt samples, but not in control and IDHmut glioma samples." (PMID 35563134, 2022).
gastric cancer (8 papers, 2017 to 2022). A primary or metastatic malignant neoplasm involving the stomach. "Although several studies have demonstrated that HOXA-AS2 promotes tumor proliferation by serving as an “miRNA sponge”, it has also been shown to enhance gastric cancer proliferation by epigenetically silencing the expression of p21, plk3, and DDIT3." (PMID 34511122, 2021). "HOXA-AS2 expression is upregulated in gastric cancer and is related to tumor size and pathological stage and patient prognosis." (PMID 32760226, 2020). "HOXA-AS2 is previously found to be overexpressed in gastric cancer and promotes its cell proliferation;26 however, its molecular mechanism and downstream targets involving in regulation of CRC cells phenotype is not known." (PMID 28112720, 2017). "Long non-coding RNA HOXA-AS2 promotes gastric cancer proliferation by epigenetically silencing P21/PLK3/DDIT3 expression by binding with EZH2 (enhaner of zeste homolog 2)." (PMID 29221147, 2017). "HOXA-AS2 is previously found to be overexpressed in gastric cancer (GC) and promotes GC cells proliferation." (PMID 28112720, 2017).
promyelocytic leukemia (6 papers, 2016 to 2024). "HOXA‐AS2 was first reported as an apoptosis repressor in all transretinoic acid‐treated NB4 promyelocytic leukaemia cells." (PMID 33683826, 2021). "HOXA-AS2 was initially determined in all-trans retinoic acid-treated NB4 promyelocytic leukemia cells." (PMID 32519740, 2020). "HOXA-AS2 acts as an apoptosis repressor in promyelocytic leukemia cells, and SNHG1 has also been suggested as a new biomarker for lung cancer and prostate cancer." (PMID 27966444, 2016). "For example, HOXA-AS-2 has been demonstrated to repress apoptosis in promyelocytic leukemia cells." (PMID 26800519, 2016).
bladder cancer (5 papers, 2020 to 2024). "In addition, miR‐125b is down‐regulated by lncRNA HOXA cluster antisense RNA 2 (HOXA‐AS2) in bladder cancer." (PMID 33332677, 2021). "This study also revealed that miR-125 b is a downstream target of HOXA-AS2, that HOXA-AS2 downregulates miR-125 b, and that interactions between HOXA-AS2, miR-125 b, and Smad2 are important for HOXA-AS2's functional role in mediating bladder cancer cells' stemness, migration, and invasion." (PMID 39170516, 2024).
gallbladder carcinoma (4 papers, 2020 to 2022). "HOXA-AS2 has important research significance in the study of potential diagnostic and therapeutic targets for gallbladder cancer." (PMID 36299503, 2022). "HOXA-AS2 may serve as a potential diagnostic and therapeutic target for gallbladder cancer in clinic." (PMID 36299503, 2022). "The expression of HOXA-AS2 in gallbladder carcinoma tissues was significantly higher than that in adjacent tissues (p < 0.05)." (PMID 36299503, 2022). "In the TCGA database, the expression of HOXA-AS2 was analyzed in normal tissues and gallbladder cancer tissues, and it was found that HOXA-AS2 was abnormally expressed in gallbladder cancer tissues." (PMID 36299503, 2022). "The expression of HOXA-AS2 in the clinical tissues of different stages of gallbladder cancer was higher than that in the corresponding normal tissues." (PMID 36299503, 2022). "HOXA-AS2 was highly expressed in multiple gallbladder cancer cell lines." (PMID 36299503, 2022). "HOXA-AS2 is abnormally expressed in gallbladder cancer cells." (PMID 36299503, 2022). "The results of in vitro cell function experiments showed that interfering with the expression of HOXA-AS2 could inhibit the speed of in vitro migration of gallbladder cancer cells and the ability to invade other cells." (PMID 36299503, 2022). "After successful knockout of HOXA-AS2 by lentiviral transfection, the expression of HOXA-AS2 in gallbladder cancer cell lines was significantly decreased." (PMID 36299503, 2022).
hepatocellular carcinoma (4 papers, 2021 to 2022). A malignant tumor that arises from hepatocytes. "Due to the abnormal expression of HOXA-AS2 in hepatocellular carcinoma and other malignant tumors, the conclusion of this study may also be applicable to other tumor tissues." (PMID 36299503, 2022).
leukemia (4 papers, 2017 to 2023). A malignant (clonal) hematologic disorder, involving hematopoietic stem cells and characterized by the presence of primitive or atypical myeloid or lymphoid cells in the bone marrow and the blood. "qRT-PCR results showed that HOXA-AS2 was highly expressed in many leukemia cell lines (KG-1, NB4, U937, HL-60, and THP-1 cells) compared to the normal human monocytes." (PMID 33268767, 2020). "HOXA cluster antisense RNA 2 (HOXA-AS2) shows high levels in leukemia cells." (PMID 37190145, 2023).
non-small cell lung carcinoma (3 papers, 2021 to 2022). A group of at least three distinct histological types of lung cancer, including non-small cell squamous cell carcinoma, adenocarcinoma, and large cell carcinoma. "HOXA-AS2 has been well established to be remarkably highly present in various tumor carcinogenesis including prostate cancer, non-small cell lung cancer and type I endometrial carcinoma." (PMID 35387643, 2022). "Several studies described HOXA-AS2 as an oncogene that promoted the malignant proliferation of non-small cell lung cancer cells." (PMID 33430870, 2021). "HOXA-AS2 has even been found to play a carcinogenic role in the pathophysiology of various cancers, including pancreatic cancer, non-small cell lung cancer, and osteosarcoma." (PMID 33430870, 2021).
endometrial carcinoma (2 papers, 2020 to 2022). A malignant tumor arising from the epithelium that lines the cavity of the uterine body. "This study aimed to explore whether HOXA-AS2 has a role in endometrial cancer and whether miR-302c-3p is involved in its underlying mechanism of action." (PMID 32760226, 2020). "This study demonstrated that HOXA-AS2 is highly expressed in endometrial cancer tissues and promotes the proliferation and invasion of type I endometrial cancer cells by inhibiting apoptosis." (PMID 32760226, 2020). "HOXA-AS2 levels were significantly increased in endometrial cancer specimens compared to normal endometrial specimens." (PMID 32760226, 2020). "To investigate the function of HOXA-AS2 in endometrial cancer, we transfected Ishikawa cells with four different HOXA-AS2 siRNAs to silence HOXA-AS2." (PMID 32760226, 2020). "Upregulation of HOXA-AS2 may promote cell proliferation and invasion, increase the fraction of S-phase cells, and inhibit apoptosis in type I endometrial cancer." (PMID 32760226, 2020). "Previous studies have demonstrated that HOXA-AS2 plays a catalytic role in endometrial cancer." (PMID 32760226, 2020). "Thus, HOXA-AS2 may affect malignant behavior of endometrial cancer by regulating miR-302c-3p expression." (PMID 32760226, 2020). "We test expression levels of HOXA-AS2, miRNA-302c-3p, the transcription factor zinc finger X-chromosomal protein (ZFX), and the chitinase-like protein YKL-40 in endometrial carcinoma by qRT-PCR and western blotting." (PMID 32760226, 2020). "In type I endometrial cancer cells, YKL expression was regulated by ZFX, HOXA-AS2, and miR-302c-3p at both the protein and mRNA levels." (PMID 32760226, 2020). "However, the roles of HOXA-AS2 in endometrial cancer remain unclear." (PMID 32760226, 2020).
malignant glioma (2 papers, 2022 to 2023). A grade III or grade IV glioma arising from the central nervous system. "In all cancer types where it has been studied, including malignant glioma, HOXA-AS2 has been found to have oncogenic functions, mainly by promoting proliferation." (PMID 35563134, 2022).
papillary thyroid cancer (2 papers, 2021 to 2022). "HOXA-AS2 regulated the HOXA-AS2/miR-520a-3p/homeobox D8 and mitogen-activated protein kinase kinase kinase 2 axis in non-small lung cancer 46, and the miR-15a-5p/homeobox A3 (HOXA3) axis in papillary thyroid cancer." (PMID 33754013, 2021).
Sepsis (2 papers, 2022 to 2025). Sepsis is defined as life-threatening organ dysfunction caused by a dysregulated host response to infection. "The ROC curve suggests that the relative expression level of HOXA‐AS2 can predict mortality risk in sepsis patients (AUC = 0.911, sensitivity = 83.33%, specificity = 85.87%." (PMID 40396530, 2025). "Study found that upregulation of HOXA‐AS2 can reverse acute kidney injury caused by sepsis." (PMID 40396530, 2025). "Moreover, our study found that HOXA‐AS2 is not only a diagnostic biomarker for sepsis but also can predicts the onset of ARDS in sepsis patients." (PMID 40396530, 2025). "Therefore, decreased HOXA‐AS2 levels could be a significant cause of ARDS in sepsis patients." (PMID 40396530, 2025). "However, whether HOXA‐AS2 is associated with the development of ARDS in sepsis remains unclear." (PMID 40396530, 2025). "The levels of HOXA‐AS2 in sepsis and ARDS patients were detected by real‐time quantitative reverse transcription PCR (RT‐qPCR)." (PMID 40396530, 2025). "This study aims to explore the mechanism of HOXA‐AS2 involved in sepsis‐related ARDS and the predictive value of this molecule for ARDS and 28‐day mortality." (PMID 40396530, 2025). "To further explore the mechanism of HOXA‐AS2 involved in the development of ARDS, we constructed a sepsis‐associated ARDS cell model by treating HPMEC cells with LPS." (PMID 40396530, 2025). "Based on previous studies, we hypothesize that HOXA‐AS2 plays a role in the occurrence and development of sepsis and sepsis‐related ARDS." (PMID 40396530, 2025). "Therefore, our results indicate that the level of HOXA‐AS2 is closely related to the mortality rate of patients with sepsis." (PMID 40396530, 2025). "A previous study suggested that lncRNA HOXA cluster antisense RNA 2 (HOXA-AS2) is downregulated in sepsis patients, CLP mouse models, and LPS-stimulated HK-2 cells while its overexpression alleviates SA-AKI by targeting miR-106b-5p and restrains the Wnt/β-catenin and NF-κB pathways." (PMID 35464083, 2022). "In our study, we found that the level of HOXA‐AS2 was significantly reduced in sepsis patients compared to non‐sepsis patients." (PMID 40396530, 2025).
thyroid cancer (2 papers, 2020 to 2023). "More importantly, some non-coding RNAs were considered as the known prognosis biomarkers in thyroid cancer, such as let-7a, LINC-PINT, H19, MALAT1 and HOXA-AS2." (PMID 37153003, 2023).
acute myeloid leukemia (1 paper, 2024). Acute myeloid leukemia (AML) is a group of neoplasms arising from precursor cells committed to the myeloid cell-line differentiation. "HOXA‐AS2 is upregulated in cervical cancer, acute myeloid leukemia, and hepatoblastoma, promoting malignant biological behavior." (PMID 37850692, 2024).
chronic obstructive pulmonary disease (1 paper, 2025). A chronic and progressive lung disorder characterized by the loss of elasticity of the bronchial tree and the air sacs, destruction of the air sacs wall, thickening of the bronchial wall, and mucous accumulation in the bronchial tree. "HOXA‐AS2 is downregulated in patients with chronic obstructive pulmonary disease (COPD) and is associated with endothelial cell proliferation." (PMID 40396530, 2025).
diabetic nephropathy (1 paper, 2021). "Studies have found that HOXA-AS2 is able to inhibit endothelial inflammation via the nuclear factor kappa B (NF-κB) pathway and that lower expression of HOXA-AS2 in diabetic nephropathy is associated with kidney injury and inflammatory response." (PMID 34511122, 2021).
gallbladder tumor (1 paper, 2022). "HOXA-AS2 was highly expressed in gallbladder tumor tissues and cells." (PMID 36299503, 2022).
glioblastoma (1 paper, 2021). The most malignant astrocytic tumor (WHO grade IV). "We also noticed that miR-885-5p, which was directly inhibited by HOXA-AS2, was downregulated during the pathological process of glioblastoma." (PMID 33430870, 2021). "In this study, HOXA-AS2 was found to be overexpressed in glioblastoma tissues and cells, to inhibit cell apoptosis, and to enhance cell proliferation, migration, invasion and the protein expression of Twist, Slug, Vimentin and MMP-2." (PMID 33430870, 2021). "The results showed that compared to adjacent healthy tissues, HOXA-AS2 expression was upregulated by twofold in glioblastoma tissues." (PMID 33430870, 2021). "This study aimed to demystify the regulatory mechanism of HOXA-AS2 in glioblastoma." (PMID 33430870, 2021). "Experimental results showed that HOXA-AS2 and RBBP4 contributed to the tumorigenesis of glioblastoma cells." (PMID 33430870, 2021). "HOXA-AS2 and RBBP4 were found to be overexpressed in glioblastoma." (PMID 33430870, 2021).
infantile epileptic encephalopathy (1 paper, 2019). an epileptic condition characterized by epileptiform abnormalities associated with progressive cerebral dysfunction. "The lncRNA HOXA Cluster Antisense RNA 2 (HOXA-AS2) modulates the expression of SCN3A, an acknowledged gene in infantile epileptic encephalopathy." (PMID 31709263, 2019).
meningioma (1 paper, 2018). A generally slow growing tumor attached to the dura mater. "HOXA-AS2 has been shown to mediate transcriptional repression of the tumor suppressor gene CDKN2A (p16INK4A), deletion of which is associated with poor meningioma survival." (PMID 30202034, 2018).
schizophrenia (1 paper, 2019). A major psychotic disorder characterized by abnormalities in the perception or expression of reality. "We also reported correlations between expressions of HOXA-AS2, MEG3 and UCA1 and age at disease onset in patients with schizophrenia." (PMID 31484957, 2019). "Expressions of HOXA-AS2, MEG3 and UCA1 were correlated with age at disease onset in patients with schizophrenia." (PMID 31484957, 2019).